TLR2 (toll like receptor 2)
Diseases named in the same sentence as TLR2 in open-access papers (continued):
Sharing a sentence is not in itself a finding about the gene and the disease.
infection (continued). "In short, TLR2 deficiency and aging enhanced the susceptibility to S. aureus bacteremia in an additive manner, as TLR2−/−/old mice had the most severe infection, with the highest mortality rate, weight loss, and bacterial load in kidneys." (PMID 36808423, 2023). "Reduced cytokine secretion and pathology observed in mice infected with plasmid-deficient C. muridarum and sacrificed early post-infection resolution has been attributed to a failure to activate TLR2." (PMID 37662000, 2023). "To understand why ascending GBS infection was lower in TLR2/4-deficient mice compared with WT mice, we evaluated the nature of immune cells that were recruited to the uterus and placenta during infection." (PMID 37747229, 2023). "TLR2-deficient mice are susceptible to infection with the Gram-positive bacteria Staphylococcus aureus, while TLR2 activation can promote NO production in hepatocytes, inducing production in a TLR2-MyD88-dependent manner." (PMID 37298614, 2023). "Collectively, these results suggest that HylB-mediated immune suppression of TLR2/4 is associated with increased rates of IL-10+ macrophages in uterine tissues, which promotes ascending infection." (PMID 37747229, 2023). "Intriguingly, in TLR2−/−/old mice, the most severely sick group with the highest weight loss and bacterial persistence in the kidneys, displayed a weak IL-6 response to infection, suggesting that advanced age has a great impact on IL-6 production." (PMID 36808423, 2023). "Evidence that TLR2 is critical to the host defense against S. aureus originated in a mouse model of intravenous septic infection, where receptor deficiency significantly accelerated host mortality." (PMID 36226943, 2022). "While chronic inflammation reduces sTLR2 levels, acute inflammation, especially driven by infection, is associated with increased levels of TLR2 and sTLR2." (PMID 36556186, 2022). "Resistant to infection confers on conventional susceptible BALB/c mice illustrates the importance of TLR2 in effective clearance of L. major parasite clearance." (PMID 35119120, 2022). "Compared to that of wild-type mice, the release of TNF-α was decreased in TLR2-deficient mice after infection with M. pneumoniae." (PMID 35372108, 2022). "Prior studies have similarly reported that planktonic infection causes upregulation of TLR2; however, expression changes after subsequent biofilm formation have not usually been examined." (PMID 35677656, 2022). "At the same time, TLR2 antibody also caused a significant down-regulation of neutrophil intracellular ROS and supernatant NETs levels in infection." (PMID 36148229, 2022). "As for lethal infection and similar to TLR2, TLR9 sensing is a critical pathogenic factor in the development of ECM in the P. berghei ANKA model." (PMID 36146602, 2022). "Trypanosoma cruzi experimental infection in TLR-deficient mice showed that TLR2, TLR4, TLR7, and TLR9 play a role in host resistance." (PMID 34336720, 2021). "In a mouse test to analyze infection caused by Candida albicans, reducing the expression of TLR2 lowers the quantity of CD4+CD25+ Treg cells and decreases the fungal burden." (PMID 34222495, 2021). "In the same study, the infection of murine cDCs with the HSV-1 TLR2* variants indicated that both, TLR2 and TLR9 sensors are activated with these variants and are associated with the secretion of proinflammatory cytokines IL-6 and IL-12." (PMID 34895058, 2021). "Four well-described SNPs that have previously been associated with the outcomes of a CT infection are: TLR2 +2477 G > A (rs5743708), NOD1 + 32656 T −> GG (rs6958571), CXCR5 + 10950 T > C (rs3922), and IL10 − 1082 A > G (rs1800896)." (PMID 33430411, 2021). "In contrast, infection of TLR2-deficient mice restored inflammatory cytokines and bacterial burden to wildtype levels, linking the shift in acyl chain composition toward UFA to detrimental immune activation in vivo." (PMID 34496007, 2021).
infection (continued). "Several studies have previously demonstrated low parasitic load and resistance to infection in TLR2- or TLR4-deficient experimental animal models." (PMID 34691019, 2021). "To further elucidate the role of TLR2 in impaired autophagy by infection, we applied TLR2-deficient macrophages to observe the potential interaction between TLR2 and the AKT/mTOR pathway." (PMID 34900761, 2021). "Infection of TLR2-deficient mice restored cytokines and bacterial burden to levels observed during infection of WT mice with WT S. aureus." (PMID 34496007, 2021). "The other immune response-related polymorphism associated with infections was TLR2 rs4696480 (c.-373+1614T>A)." (PMID 33776761, 2021). "TLRs are responsible for the recognition of pathogen-associated molecular patterns (PAMPs) during pathogen infection, such as TLR2 recognizing lipoproteins and glycolipids and TLR4 recognizing LPS." (PMID 33923441, 2021). "Studies have shown that the TLR2 and MyD88 pathways play an important role in bone loss caused by infection." (PMID 33461495, 2021). "This is the first report to describe the mechanism by which nicotine modulates TLR2/MyDD88 and exacerbates inflammation in CD smokers associated with infection." (PMID 33212859, 2020). "Second, the route and site of infection seem to influence TLR2-mediated immune responses, as reported in murine studies using TLR2-deficient mice." (PMID 33256638, 2020). "Since IL-1β expression was significantly reduced in the brain of TLR2 KO mice as well as TLR2-deficient microglia and macrophages, we next examined the functional importance of caspase-1 during S. aureus craniotomy infection using caspase-1 KO mice." (PMID 32290861, 2020). "The bacterial wall of multiple types of microorganisms causing common infections contains molecules that bind and activate TLR2." (PMID 32059733, 2020). "In fact, we observed that NOD2 deficient mice showed high TLR2 and inflammatory mediators expression during the acute phase of the infection." (PMID 32986710, 2020). "A fifth explanation is that our laboratory environment was so stressful that it overwhelmed the variation in susceptibility to infection between the TLR2 genotypes." (PMID 31040326, 2019). "To obtain explanations and genetic markers for further studies of the effect of the tlr2 mutation on infection we performed deep RNA sequencing to study the whole transcriptome profile in our mycobacterial infection model at the systems level." (PMID 31747871, 2019). "During the acute phase of infection, TLR2/4-deficient mice had lower cerebrospinal fluid concentrations of interleukin-1β, and higher interferon-γ, than their wild-type counterparts." (PMID 31700009, 2019). "This analysis revealed that most of transcriptional downregulation caused by Mm infection in control animals was abrogated by tlr2 mutation, in addition to a dampening effect on the upregulation of transcription factors and inflammatory genes." (PMID 31747871, 2019). "The analysis of differential gene expression during infection showed that there is a very pronounced effect of mutation of the tlr2 gene." (PMID 31747871, 2019). "In vitro infection with L. braziliensis caused CL monocytes to up-regulate TLR2 and TLR4 expression." (PMID 31119102, 2019). "SNEA predicted 565 and 503 pathways for tlr2+/− and tlr2−/− zebrafish that are linked to the response to infection, respectively, and 264 and 202 of them are specific for the response in tlr2+/− and tlr2−/− fish, respectively." (PMID 31747871, 2019). "Compared with WT uninfected mice, both the proportion and the absolute number of Mo/MΦs were increased in WT mice after infection, while a deficiency in TLR2 resulted in a slightly increase of Mo/MΦs and much less than that in WT-infected mice." (PMID 31297109, 2019).
infection (continued). "NF-κB target genes (i.e., C3, Chi3l1, Fas, Gadd45β, Hmox1, Ptx3, Saa3, Tlr2) were also abundant in DEGs in which upregulation during infection was impaired by CCR5-deficiency." (PMID 31506064, 2019). "Together, our results for the first time implicated the role of TLR-2 in governing two important molecular events, ER-stress and O2− generation during M. smegmatis-infection." (PMID 31444398, 2019). "Mtb primarily overactivates the TLR2 pathway and eventually causes its silencing, which leads to the unresponsiveness of macrophages to infection." (PMID 31871425, 2019). "Using this low-dose infection setting, we now demonstrate that TLR2/4 ligands generated during a coinfection with E. coli caused a NK cell-mediated suppression of the anti-viral CTL response and thereby prevented rapid virus control." (PMID 30297690, 2018). "Our most relevant finding is that the imbalance of Th17 and B cells numbers and a lower expression of TLR2 in monocytes along with cyclophosphamide use are the major risk factors for infection in SLE patients." (PMID 30692998, 2018). "These various results on the role of TLR2/9 in HSV-caused diseases indicate the need for detailed analysis in a more relevant infection model for a clear understanding." (PMID 29760708, 2018). "The variables associated with infection in multivariate analyses included anti dsDNA antibodies, absolute number of B cells and LDGs and the expression of TLR2 in total monocytes." (PMID 30692998, 2018). "Strikingly, despite the fact that the double knock-out mice were colonized by P. gingivalis, they were completely resistant to infection-driven bone resorption, suggesting an absolute requirement for TLR2 in pathologic bone loss in this model." (PMID 28848717, 2017). "First, we examined the involvement of CatS in the response of the spleen after systemic exposure to PgLPS, a TLR2 agonist, as the spleen is susceptible to infection." (PMID 28769800, 2017). "We also found that the expression of TLR2 was higher when the infection was associated with the HH condition (HH-Tm group) compared with the group that was infected, but the HH condition not induced." (PMID 28164040, 2017). "Altogether, these results clearly establish that the lack of protein glycosylation is associated with a greater induction of the TLR2-mediated inflammatory response during host-cell infection." (PMID 28801649, 2017). "The identified heterozygotes in the range of TLR2 SNP were estimated as 10 times more susceptible to develop the infection." (PMID 28118851, 2017). "In the absence of both TLR2 and MyD88, P. gingivalis persists in the oral cavity but is unable to induce bone loss, further confirming the essential role of TLR2-dependent, MyD88-independent inflammation in bone loss that develops in response to infection." (PMID 28848717, 2017). "Our findings facilitate understanding of the detailed relationship between TLR2 and T. gondii infection, and elucidate mechanisms underlying neurological changes during infection." (PMID 29136637, 2017). "Increased susceptibility or resistance to infection with C. albicans were both showed in TLR2-deficient mice, due to reduced proinflammatory cytokines production or decreased IL-10/increased IL-12 and IFN-γ production, respectively." (PMID 29238325, 2017). "A further study showed that TLR11−/− and TLR2/4 double knockout mice display relatively increased susceptibility to infection with a simultaneous decrease in IL-12 along with an increase in the number of brain cysts." (PMID 27511368, 2016). "Mitigation of TLR2 enhanced tissue necrosis in mice and impaired bacterial clearance, whereas loss of Nod2 led to decreased pathology, faster clearance of infection and increases in IL-10 and IFN-γ." (PMID 29056735, 2016). "After infection with 100 mycobacteria, TLR2 deficient mice were as resistant as were congenic control mice." (PMID 27214039, 2016).
infection (continued). "Nevertheless, a role for TLR2 is highly probable since higher loads of Toxoplasma gondii in brain tissue were observed in TLR2-deficient mice following infection with Toxoplasma gondii cysts." (PMID 27207565, 2016). "TLR2 deficient mice are more susceptible to infection than wild type mice, signifying the involvement of TLR2 in initiation of a protective immune response towards S. aureus." (PMID 26872029, 2016). "TLR2 has been implicated in the recognition of Leishmania parasites, and in playing a role during infection in vivo." (PMID 26897363, 2016). "Others showed that lipoproteins from pathogenic S. pneumoniae induces TLR2 to promote the release of TNFα from macrophages during infection." (PMID 27309732, 2016). "We observed an increased susceptibility of both TLR2- and Unc93b1-deficient animals to infection compared to WT controls." (PMID 25756897, 2015). "We demonstrate that miR-UL112-3p efficiently down-regulates endogenous TLR2 during infection, causing significant inhibition of the downstream signaling cascade." (PMID 25955717, 2015). "A recent study in mice has shown that infection with L. infantum resulted in the increased transcription of TLR2 and TLR4 and associated cytokines." (PMID 26465878, 2015). "Pro-inflammatory cytokine production requires TLR2 signaling and TLR2 KO mice are more susceptible to sub-lethal infection with LVS." (PMID 25250027, 2014). "Given that TNF production by activated macrophages is partially TLR2-dependent, we next tested the ability of TNF-deficient BMMφ to express cathelicidin upon infection with M. avium or TLR2 activation." (PMID 25400920, 2014). "We previously showed that TLR2/4dko mice are sensitive to pathogenic Leptospira and die from the infection." (PMID 24498450, 2014). "TLR2 expression is differentially regulated by inflammatory mediators, and some infections have been associated with increased TLR2 expression." (PMID 24892697, 2014). "Humans with TLR2 Arg753Gln show increased susceptibility to tuberculosis and infections by Gram-positive organisms." (PMID 23873783, 2013). "For example, loss of either TLR2 (Toll-like receptor 2) or MyD88 results in reduced survival as a result of tularemic infection." (PMID 23349802, 2013). "TLR2/9 knocks out mice displayed markedly enhanced susceptibility to infection in association with combined defects in pro-inflammatory cytokine production in vitro, IFN-γ recall responses ex vivo, and altered pulmonary pathology." (PMID 24176007, 2013). "Considering our observations and these previous reports, we think that the high hepatic bacterial load seen in TLR2-deficient mice at the late phase of infection (3 d post-infection) was due to a lasting decrease in IL-10 release." (PMID 24058538, 2013). "Our data show for the first time that lethal infection is associated with the upregulation of surface and intracellular PRRs, including TLR2, Nod1, and Nod2." (PMID 23526993, 2013). "This probably explained the susceptibility of TLR9−/− mice during the infection since TLR2 cannot assume IL-12/IL-23p40 production required for mice survival in such situation." (PMID 23650544, 2013). "During the first 2 d post-infection, WT mice and TLR2-deficient mice displayed the same levels of bacterial load in livers as well as equal accumulation of neutrophils and macrophages." (PMID 24058538, 2013). "In this study, we further confirmed the increased numbers and function of CD4+ and CD8+ T cells in mice with deficiency of TLR2 with the infection of Schistosoma japonicum." (PMID 24376539, 2013). "During Schistosoma japonicum infection, TLR2, PD-L1 and PD-L2 expression on DCs were persistently upregulated till 6 weeks after infection in wild-type mice, whereas TLR2 deficiency results in decreased PD-L2 expression on DCs at 6 weeks after infection." (PMID 24376539, 2013). "For example, TLR2 knockout mice are highly susceptible to infections by Staphylococcus aureus and Streptococcus pneumoniae." (PMID 24302927, 2013).
infection (continued). "In contrast, greater IL-6 elevation was seen in the organs of infected TLR2-deficient animals during their survival period; at 3 d post-infection, the hepatic and blood IL-6 levels were 5.5- and 2.9-fold higher than those in infected WT mice, respectively." (PMID 24058538, 2013). "Our data showed that increased TLR2 expression is correlated with infection with Brucella, indicating a possible loss of synaptic stability in white matter." (PMID 24350061, 2013). "In contrast, TLR2-deficient mouse death began early at 2 d post-infection, and all succumbed to infection within 4 d post-infection." (PMID 24058538, 2013). "WT and TLR2-deficient mice also showed a same slight increase in bacterial count within 3 d post-infection in kidneys; thereafter, the WT mice exhibited reduced bacterial counts in the kidneys." (PMID 24058538, 2013). "TLR2 deficiency leads to reduced phagocytic activity of neutrophils and a loss of control of infection and inflammation." (PMID 22724018, 2012). "Immunosuppressed TLR2−/− mice (neutropenic and treated with antibiotics) have an increased susceptibility to A. fumigatus following intratracheal infection and increased fungal burden in the lung in comparison to wild-type immunosuppressed animals." (PMID 23189270, 2012). "Infection with strains of differing pathogenic potential had similar effects on TLR2 expression at the cell surface, ruling out the possibility that the absence of cytokine responses were a result of differences in TLR2 expression." (PMID 23202459, 2012). "Another study of Turkish pediatric patients also associated the TLR2 R753Q heterozygotes with TB, citing an over 5-fold increased risk of infection (OR = 5.05, P ≤ 0.001)." (PMID 22529866, 2012). "Similar data were demonstrated previously and that study also showed that the TLR2/4 double-deficient mice succumbed to the infection." (PMID 22096480, 2011). "TLR2/4 double deficient mice lost considerably more weight at day 12 post infection than wild type mice despite increased IFNγ levels." (PMID 22096480, 2011). "Enhanced IFNγ-responses by C. pneumoniae-specific CD4+ T-cells in TLR2/4 double-deficient mice are best explained by an impaired infection-associated expansion of CD4+CD25+Foxp3+ regulatory T-cells." (PMID 22096480, 2011). "In this regard, our data cannot exclude the role of other TLRs (which also signal through MyD88 such as TLR2) in the regulation of apoptosis upon infection with the pathogenic meningococcal isolates." (PMID 22144896, 2011). "By 14 days post infection, inflammation was still visible in the TLR2-deficient mice while inflammation was largely resolved in the wild type mice." (PMID 21695078, 2011). "Surprisingly, it appears TLR2 can play either a protective or detrimental role in disease caused by herpes simplex virus (HSV) depending on the context of the infection." (PMID 21994762, 2011). "Our observations lead us to conclude that the role of TLR2 in host defense is contextual, and that while TLR2 deficiency results in decreased virulence of infection in the genital tract, it has the opposite effect in the lung." (PMID 21695078, 2011). "We first examined bone marrow derived macrophages from C57BL/6 vs. TLR2-deficient mice on the same background for induction of various cytokines in response to productive infection with C. muridarum." (PMID 21695078, 2011). "To confirm the observation that TLR2-deficient mice experienced more severe lung inflammation in response to their infection, we examined the recruitment of neutrophils and macrophages to the lung using flow cytometry." (PMID 21695078, 2011). "Studies using an intraperitoneal infection model found TLR2 deficient neonates were protected from lethal HSV-1 encephalitis compared to wild type mice." (PMID 21994762, 2011). "We therefore compared MAP kinase signalling following L. mexicana promastigote infection in macrophages deficient in TLR-2 and TLR-4 or both." (PMID 21664694, 2011).